SURF1 (SURF1 cytochrome c oxidase assembly factor)
Description:
Component of the MITRAC (mitochondrial translation regulation assembly intermediate of cytochrome c oxidase complex) complex, that regulates cytochrome c oxidase assembly.
Synonyms: SHY1; CMT4K; MC4DN1
Tractability: Antibody: UniProt predicts a signal peptide or a membrane-spanning region. PROTAC: ubiquitination databases record sites on it; its protein half-life has been measured.
Gene: Protein-coding gene on chromosome 9 (133,351,758 to 133,356,676, reverse strand). Ensembl gene ENSG00000148290.
Subcellular location: Mitochondrion inner membrane
Pathways (Reactome):
Metabolism: Complex IV assembly
Gene Ontology:
Molecular function: protein binding; cytochrome-c oxidase activity
Biological process: mitochondrial respiratory chain complex IV assembly; aerobic respiration; respiratory chain complex IV assembly; proton transmembrane transport
Cellular component: mitochondrion; mitochondrial inner membrane; respiratory chain complex; membrane
Genetic constraint (gnomAD): Loss-of-function variants: 44 observed, 36.27 expected, observed/expected ratio (o/e) 1.21, 90% interval 0.95 to 1.56. The synonymous counts are far from expectation, so gnomAD's model fits this gene poorly and the ratio says little. Missense variants: 453 observed, 382.73 expected, observed/expected ratio (o/e) 1.18, 90% interval 1.1 to 1.28. Synonymous variants: 188 observed, 146.76 expected, observed/expected ratio (o/e) 1.28, 90% interval 1.14 to 1.45.
Gene-disease validity (ClinGen):
ClinGen rates the evidence that SURF1 causes each of these diseases.
Leigh syndrome (autosomal recessive): Definitive. A progressive neurological disease defined by specific neuropathological features associating brainstem and basal ganglia lesions.
mitochondrial disease (autosomal recessive): Definitive.
Homologues: Orthologues: chimpanzee SURF1 (99% identical), macaque SURF1 (96% identical), guinea pig SURF1 (84% identical), dog SURF1 (84% identical), mouse Surf1 (79% identical), pig SURF1 (76% identical), zebrafish surf1 (61% identical), tropical clawed frog surf1 (61% identical), Drosophila melanogaster Surf1 (42% identical), Caenorhabditis elegans sft-1 (35% identical). Paralogues in human: SURF4 (15% identical).
Diseases named in the same sentence as SURF1 in open-access papers:
SURF1 is named in the same sentence as 70 diseases in open-access papers, as found by Europe PMC text mining. Sharing a sentence is not in itself a finding about the gene and the disease. The quoted sentences say what the papers report.
Leigh syndrome (66 papers, 2008 to 2026). "One of the most common causes of Leigh syndrome are genetic mutations in the surfeit locus protein 1 (SURF1) gene, and these mutations are typically autosomal recessive." (PMID 40893166, 2025). "Patients with SURF1‐related Leigh syndrome, multiple acyl‐CoA dehydrogenase deficiency (MADD), MELAS, and mitochondrial recessive ataxia syndrome (MIRAS) were the only patients presenting restricted diffusion." (PMID 39080972, 2025). "Gastrointestinal symptoms were even more prevalent in patients with COX-deficient Leigh syndrome caused by mutations in the SURF1 gene." (PMID 40149709, 2025). "The majority of SURF1-associated Leigh syndrome cases follow a typical course, leading to early mortality before the age of ten." (PMID 40149709, 2025). "To date, over sixty distinct SURF1 mutations have been identified as causes of SURF1-associated Leigh syndrome." (PMID 40149709, 2025). "The SURF1 c.845_846delCT mutation, which is rare in other ethnic groups, is a founder allele in Polish (78% of pathogenic alleles in SURF1 gene) and Russian (65% of pathogenic alleles) patients with Leigh syndrome." (PMID 39273284, 2024). "Genetic testing confirmed compound heterozygosity for two pathogenic variants in SURF1 implicated in Leigh syndrome." (PMID 39066889, 2024). "The major clinical presentation of SURF1-associated Leigh syndrome is cerebellar signs such as ataxia (40.6%)." (PMID 36675121, 2023). "Surf1 encodes an integral membrane protein, and mutations in Surf1 cause Leigh syndrome, a severe neurological disorder characterized by progressive loss of mental and movement abilities." (PMID 36574593, 2023). "The most common cause of Leigh syndrome in Russian patients is pathogenic variants in the SURF1 gene (44.3%)." (PMID 36675121, 2023). "The median age at death of our Leigh syndrome participants with pathogenic SURF1 variants is lower than that observed from the cross‐sectional study, which had different inclusion criteria, resulting in a broader spectrum of phenotypes being recruited." (PMID 34716721, 2022). "Leigh syndrome was the most common among mitochondrial diseases with an underlying SURF1 gene pathogenic mutation in 62%." (PMID 36468010, 2022). "The difference in survival in those with high disease burden (NPMDS > 25) was also statistically significant (χ2 = 25.7, p < 0.001), and again children with Leigh syndrome due to recessive SURF1 pathogenic variants fared worse." (PMID 34716721, 2022). "Children with Leigh syndrome due to pathogenic SURF1 variants in this cohort have poorer outcomes when followed up longitudinally." (PMID 34716721, 2022). "Considering the rarity of SURF1-associated Leigh syndrome, its’ poor outcomes with early mortality, and its’ difficulty to treat, we review in detail the genotype and phenotype, the typical and atypical courses of Leigh syndrome, and treatment." (PMID 34943053, 2021). "Here, we review the literature concerning SURF1-associated Leigh syndrome, and the phenotype and genotype of SURF1-associated Leigh syndrome in children." (PMID 34943053, 2021). "Deficiency of OXPHOS complex IV (cytochrome c oxidase; COX) accounts for approximately 15% of all Leigh syndrome diagnoses, with mutations in SURF1 being the most commonly reported." (PMID 34299348, 2021). "SURF1 defects account for a considerable proportion of Leigh syndrome cases associated with cytochrome c oxidase (COX) deficiencies." (PMID 34680998, 2021). "Mutations in SURF1 cytochrome C oxidase assembly factor (SURF1) are associated with Leigh syndrome, a rare progressive neurodegenerative disorder caused by mitochondrial cytopathy." (PMID 33918445, 2021). "Mutations in this gene are a cause of Surf1 protein deficiency, a recessively inherited severe mitochondrial neurological disorder, and is the most frequent cause of Leigh syndrome (LS) associated with cytochrome c oxidase (COX, complex IV) deficiency." (PMID 33594065, 2021).
Leigh syndrome (continued). "Out of 110 patients with Leigh syndrome who met the clinical criteria, three patients showed nDNA mutation and all had SURF1 gene mutation." (PMID 32351444, 2020). "Remarkably, SURF1 pathological variants account for the most common genetic etiology of Leigh syndrome, even though over 79 genes have been documented to cause this disorder." (PMID 33426505, 2020). "The most common nuclear-encoded gene inducing Leigh syndrome is SURF1, which is an assembly factor for Complex IV." (PMID 33426505, 2020). "In patients with Leigh syndrome due to mutations others than SURF1 and POLG, hypertrophic olivary degeneration is hardly found with the exception of one case of PDH deficiency." (PMID 25887401, 2015). "Mitochondria from individuals with mutations in the Surfeit locus protein 1 (Surf1) gene show only partially assembled cytochrome C oxidase complexes (3rd complex of the electron transport chain) resulting in the lethal Leigh syndrome in humans." (PMID 26442263, 2015). "She presented the history of a family with children suffering from Leigh syndrome, caused by mutations in the SURF1 gene which encodes the protein surfeit locus protein 1 (Surf1)." (PMID 28357294, 2015). "The natural history of Leigh syndrome has been described for the subgroups of SURF1 deficiency, cytochrome c oxidase deficiency due to LRPPRC mutations and complex I deficiency." (PMID 24731534, 2014). "In particular, SURF1-deficient Leigh syndrome was found to have a more favorable survival outcome compared to Leigh syndrome associated with complex I-deficiency or LRPPRC mutations." (PMID 24731534, 2014). "Mutations in human SURF1 are associated with Leigh syndrome, a neurodegenerative condition of the brain caused by cytochrome oxidase (COX) deficiency." (PMID 24472117, 2013). "Review of 44 cases with SURF1 deficiency revealed that 32 patients met the criteria for Leigh syndrome and 12 patients were classified as “Leigh-like” due to atypical or normal radiological features or where neuroimaging was not available." (PMID 23829769, 2013). "SURF1 deficiency is a recessively inherited mitochondrial disorder and is the most frequent cause of Leigh syndrome (LS) associated with cytochrome c oxidase (COX, complex IV) deficiency." (PMID 23829769, 2013). "In several cases, Complex I (CI) mutations, either in structural subunits or assembly factors, are associated with Leigh syndrome, but the single most frequent gene causing nDNA Leigh syndrome is loss of function mutations in SURF1, an assembly factor of cytochrome c oxidase IV." (PMID 40149709, 2025). "Hypertrichosis is a common feature in Leigh syndrome patients with SURF1 mutations." (PMID 40149709, 2025). "Leigh syndrome patients with SURF1 deficiency often show elevated blood lactate levels." (PMID 40893166, 2025). "Cytochrome c oxidase deficiency due to loss of function variants in SURF1 has been implicated in both Leigh syndrome (the clinical manifestation of mitochondrial complex IV deficiency, nuclear type 1; OMIM 220110) and Charcot-Marie-Tooth disease (type 4 K; OMIM 616684)." (PMID 39066889, 2024). "More than 100 different variants are recorded in SURF1-associated Leigh syndrome, and although neuroimaging features may vary, SURF1-related phenotypes often spare the putamina, favouring greater involvement of the brainstem." (PMID 39066889, 2024). "In addition, attempts were made to create a model of Leigh syndrome with associated complex IV deficiency in mice and pigs with knockout of the Surfeit Locus Protein 1 (SURF1) gene, which is a cytochrome c oxidase assembly factor." (PMID 36831068, 2023).
Leigh syndrome (continued). "This protein was later renamed Coa4 (cytochrome c oxidase assembly number 4) and its involvement in CIV assembly was confirmed being identified as a genetic suppressor of mutations in Shy1 modeling those found in the human ortholog SURF1 and associated with Leigh syndrome." (PMID 34557489, 2021). "The first cases of Leigh syndrome caused by SURF1 mutations were described in 1998." (PMID 33238568, 2020). "Besides Leigh syndrome, there are also reports of SURF1 mutations associated with Charcot–Marie–Tooth disease." (PMID 33238568, 2020). "SURF1-deficient mice activate mitochondrial stress responses, such as the mtUPR (mitochondrial unfolded stress response), while pathogenic variants in SURF1 are linked to COX-deficient Leigh syndrome in human resulting from defective CIV assembly and the accumulation of subcomplexes." (PMID 32481479, 2020). "Most notably, contrary to expectation, mice carrying a homozygous knockout of the cytochrome c assembly factor (Surf1) - a gene in which mutations cause Leigh syndrome - displayed significantly prolonged lifespan and enhanced memory, and were protected against Ca2+-dependent neurodegeneration." (PMID 31454791, 2019). "SURF1 deficiency is the most common single cause of Leigh syndrome in the UK population, and careful documentation of the clinical features may lead to increased recognition and more rapid diagnosis of affected children." (PMID 23829769, 2013). "Indeed, mutations in SURF1 appear to be the most common cause of the classical presentation of Leigh syndrome, although they have also been identified in a case of leukodystrophy, a mild encephalopathy without the typical MRI-identifiable lesions, and several cases of Charcot–Marie–Tooth disease." (PMID 38612624, 2024). "Loss-of-function mutations in surfeit locus protein 1 (SURF1) results in a severe pediatric mitochondrial disease called Leigh syndrome (LS), for which there is no cure as of yet." (PMID 37146581, 2023). "SURF1-deficient skeletal muscle of patients with Leigh syndrome (LS) shows a reproducible and characteristic pattern of changes in light and electron microscopy that are potentially helpful in diagnosis." (PMID 17908801, 2008). "Previously, we reported that a gene replacement therapy for SURF1-related Leigh syndrome was developed, which showed improved complex IV activity and restored exercise-induced lactate acidosis, as well as a high safety profile in wild-type (WT) mice." (PMID 40893166, 2025). "In most cases, patients with SURF1-related Leigh syndrome show 10%–30% remaining COX activity as examined with muscle or skin fibroblasts." (PMID 40893166, 2025). "Surfeit locus protein 1 (SURF1)-related Leigh syndrome is an early-onset neurodegenerative disorder characterized by a reduction in complex IV activity that disrupts mitochondrial function." (PMID 40893166, 2025). "In this study, we re-engineered a previously developed gene therapy for SURF1-related Leigh syndrome, and demonstrated that the new design is equally effective with minimal toxicity." (PMID 40893166, 2025). "Here, we report the development of an improved gene therapy for SURF1 Leigh syndrome by utilizing a different promoter and polyadenylation sequence." (PMID 40893166, 2025). "We propose this new vector design as a promising therapeutic candidate for SURF1-related Leigh syndrome, warranting further translational studies." (PMID 40893166, 2025). "We then report an equally effective but safer gene therapy design that represents a promising therapeutic candidate for SURF1-related Leigh syndrome." (PMID 40893166, 2025). "The monogenic nature of SURF1-related Leigh syndrome supports the possibility of a gene replacement therapy." (PMID 40893166, 2025). "Ling and colleagues identified transgene overexpression-induced cytotoxicity in their previously reported AAV9- based gene replacement therapy for SURF1-related Leigh syndrome." (PMID 40893166, 2025).
Leigh syndrome (continued). "SURF1 disorders are most common and responsible for severe forms of COX deficiency, such as Leigh syndrome." (PMID 38474355, 2024). "The human homologue of Shy1, SURF1, is implicated in severe neurological disorders and Leigh syndrome." (PMID 37859837, 2023). "Hypoxia, which was shown to be beneficial in mouse models of NDUFS4−/− Leigh syndrome, resulted in increased glycolysis and exacerbated the neuronal outgrowth phenotypes in the SURF1 neurons." (PMID 34299348, 2021). "Hypertrichosis, a recognised feature of some forms of mitochondrial disease (most notably SURF1-Leigh syndrome), was a noted feature in two Palestinian children." (PMID 34012134, 2021). "While these animal models provide evidence of COX deficiency due to loss of SURF1 protein, they were unable to recapitulate the majority of clinical features in SURF1 Leigh syndrome patients." (PMID 34680998, 2021). "Mutations in SURF1 can cause Leigh syndrome (LS), a subacute neurodegenerative encephalopathy, characterized by early onset (infancy), grave prognosis, and predominant symptoms presenting in the basal ganglia, thalamus, brainstem, cerebellum, and peripheral nerves." (PMID 34943053, 2021). "Pathogenic variants in SURF1, a nuclear-encoded gene encoding a mitochondrial chaperone involved in COX assembly, are one of the most common causes of Leigh syndrome (LS)." (PMID 33134083, 2020). "For example, similar alteration of COX oxygen affinity can be observed in cells with pathological mutations in the SURF1 protein, which lead to pathologic COX deficiency and is clinically associated with Leigh’s syndrome." (PMID 32075102, 2020). "In humans, the SURF1 mutation leads to COX deficiency (>90%) in multiple tissues and causes a fatal neurological disorder, Leigh syndrome." (PMID 29696791, 2018). "Mutations of human SURF1, encoding a highly conserved protein located in the inner mitochondrial membrane (18, –, 25), cause COX-defective Leigh syndrome (LSCOX, OMIM 256000)." (PMID 25164807, 2014). "SURF1 deficiency, a monogenic mitochondrial disorder, is the most frequent cause of cytochrome c oxidase (COX) deficient Leigh syndrome (LS)." (PMID 23829769, 2013). "While there would undoubtedly be some distortion of normal distribution of clinical data of Leigh syndrome populations due to the higher number of SURF-1 related Leigh syndrome entries, this is expected to diminish as the size and genetic diversity of the registry increases." (PMID 37667390, 2023). "Thus far, investigations have been reported for Leigh syndrome iPSC-derived neuronal cell types possessing mutations in: MT-ATP6, MT-ND5, NDUFS4 and SURF1, and SCO2." (PMID 34299348, 2021). "When patients present with Leigh syndrome or leukodystrophy, SURF1 should be considered." (PMID 34943053, 2021). "The WES findings for two patients (patient 10 and patient 6) showed disease-causing variants in OPA1 and SURF1, respectively, and these findings were correlated with their corresponding syndromic presentations of autosomal dominant optic atrophy (ADOA) and Leigh syndrome." (PMID 32907636, 2020). "Pathogenic SURF1 variants usually present with Leigh Syndrome (LS) and are the most common cause of COX deficiency-associated LS (I.-C." (PMID 33134083, 2020). "The genes that result to Leigh syndrome are ETC—related genes and include MT-ND (Complex I), SURF1 (Complex IV), ATP6 (Complex V), NDUFS1 (Complex I), SDHA (Complex II), UQCRQ (Complex III), COX10 (Complex IV), and ATP5E (Complex V)." (PMID 40728973, 2025). "As we pointed out in our previous publication, one limitation of developing a gene therapy for SURF1-related Leigh syndrome is that the available mouse model does not recapitulate overt phenotypes of the human disease." (PMID 40893166, 2025). "This patient showed an extremely severe clinical course, which was not typical for the SURF1-related Leigh disease." (PMID 37095554, 2023).
Leigh syndrome (continued). "Crucially, bezafibrate treatment allowed the SURF1-neurons to undergo the metabolic switch from glycolysis to OXPHOS and nearly ameliorated all mitochondrial functional defects, supporting bezafibrate as a possible therapeutic option for SURF1-related Leigh syndrome." (PMID 34299348, 2021). "Mice lacking active SURF1 protein (Surf1−/− mice) were developed to study Leigh Syndrome." (PMID 29696791, 2018).
epilepsy (5 papers, 2019 to 2023). A brain disorder characterized by episodes of abnormally increased neuronal discharge resulting in transient episodes of sensory or motor neurological dysfunction, or psychic dysfunction. "Epilepsy, as another neurological sign, was observed in 31.6% (12/38) of patients with mtDNA variants and only in 9.4% (2/32) of the SURF1 gene patients." (PMID 36675121, 2023). "This is consistent with the literature data, since epilepsy is not a characteristic symptom for SURF1 patients, while it is common for mtDNA mutations." (PMID 36675121, 2023). "Some patients may only have nervous system abnormalities or epilepsy as the main manifestation; however, patients previously reported with epilepsy bearing variants in RARS2 and SURF1 are rare." (PMID 34992632, 2021). "Epilepsy has not been reported as a common symptom in the SURF1 gene defect." (PMID 33134083, 2020).